RN7SKP142 (RN7SK pseudogene 142)
Gene: Miscellaneous RNA gene on chromosome 16 (51,671,236 to 51,671,563, reverse strand). Ensembl gene ENSG00000223168.
Homologues: Orthologues: chimpanzee 7SK (99% identical), guinea pig 7SK (60% identical). Paralogues in human: 7SK (70% identical), RN7SKP245 (70% identical), RN7SKP203 (68% identical), RN7SKP78 (68% identical), RN7SKP146 (67% identical), RN7SKP133 (67% identical), RN7SKP187 (67% identical), RN7SKP217 (67% identical), RN7SKP90 (67% identical), RN7SKP176 (67% identical), RN7SKP291 (67% identical), RN7SKP44 (67% identical), and 284 more.